DSCC1 (DNA replication and sister chromatid cohesion 1)
Diseases named in the same sentence as DSCC1 in open-access papers (continued):
Sharing a sentence is not in itself a finding about the gene and the disease.
cancer (12 papers, 2012 to 2024). A tumor composed of atypical neoplastic, often pleomorphic cells that invade other tissues. "Gain- and loss-of-function experiments demonstrated that DSCC1 is involved in the viability of cancer cells in response to genotoxic stimuli." (PMID 24465681, 2014). "Yamaguchi et al35 reported that DSCC1 is important for the survival of cancer cells in response to γ-irradiation." (PMID 31762824, 2019). "We here showed for the first time that DSCC1 plays an important role in survival of human cancer cells, since enhanced expression of DSCC1 induced survival of cancer cells in response to γ-irradiation, topoisomerase I inhibitor, and DNA-intercalator." (PMID 24465681, 2014). "Immunohistochemical analysis unexpectedly depicted accumulated DSCC1 in the cytoplasm and nucleus of DSCC1-positive cancer cells, although Dscc1 was reported to play a role in the establishment of cohesion during DNA replication in the yeast." (PMID 24465681, 2014). "Consistent with the immunohistochemical staining of cancer tissues, DSCC1 protein was localized in both cytoplasm and nucleus." (PMID 24465681, 2014). "DSCC1 expression also has a substantial positive association with the presence of immune cell types (CD8+ T cells, CD4+ T cells, and B cells), possibly altering the tumor microenvironment and leading to cancer development." (PMID 39768811, 2024). "Given the significant role of abnormal transcriptional regulation in cancer development, we hypothesized that aberrant transcription leads to increased DSCC1 expression in GC." (PMID 39309429, 2024). "All these previous findings demonstrate the potential role of DSCC1 in cancer biology." (PMID 39768811, 2024). "All this evidence supports the carcinogenic activity of DSCC1 in different cancer types." (PMID 39768811, 2024). "In addition, the expression of DSCC1 was closely correlated with the features of cancer stem cells of LUAD." (PMID 37742009, 2023). "The results indicated that DSCC1 was localized to the nucleus and cytosol in tumor regions, with DSCC1 staining being particularly strong in the cytosol (P<0.001, cancer vs. normal)." (PMID 31762824, 2019). "Since E2F1 conferred resistance to genotoxic insults, we further investigated whether elevated DSCC1 expression plays a role in the sensitivity of cancer cells to genotoxic stimuli." (PMID 24465681, 2014). "To address the role of its elevated expression in CRC cells, we investigated whether DSCC1 is involved in the proliferation of cancer cells." (PMID 24465681, 2014). "Therefore, DSCC1 emerges as a crucial regulator of cancer cell proliferation and migration." (PMID 39309429, 2024). "In line with such a functional relationship, POLE3, POLE4, DSCC1, CHTF18, and CHTF8 show a high correlation in co-essentiality score across cell lines as determined by the Cancer Dependency Map database." (PMID 36622344, 2023). "In this study, we observed that DSCC1 interacted and coexpressed with HSP90AB1 in LUAD which promoted cancer progression, indicating that HSP90AB1 might act as a molecular chaperone and be involved in DSCC1-promoted LUAD progression." (PMID 37742009, 2023). "The results of the present study and previous data 35 suggest that DSCC1 was unaffected by MG132 administration, and that DSCC1 stability is not likely to serve a major role in cancer cells." (PMID 31762824, 2019). "We found that the number of viable cells transfected with DSCC1#1 or DSCC1#2 shRNA was significantly decreased compared to those transfected with EGFP, DSCC1#1scr, or DSCC1#2scr shRNA, indicating that DSCC1 plays a role in the viability of cancer cells." (PMID 24465681, 2014). "In the end, we identified six genes (DLGAP5, DSCC1, SSBP1, UBE2C, SNRPD1, and SMO) with a vital role in prevention of cell death in both cell lines and hence six potential drug targets for silencing in cancer therapy." (PMID 23251412, 2012).
tumor (11 papers, 2010 to 2024). "High expression of DSCC1 was significantly associated with large tumor size, high tumor grade, ER negativity, PR negativity, and high levels of Ki67." (PMID 39768811, 2024). "Furthermore, statistical analysis of clinicopathological data from all GC patients revealed that high DSCC1 expression was closely linked to tumor size, depth of invasion, lymph nodes metastasis, distant metastases, TNM stage, and degree of differentiation (P < 0.05)." (PMID 39309429, 2024). "We established a subcutaneous tumor model in nude mice by injecting NCI-N87 cells transfected with either sh-Ctrl or sh-DSCC1." (PMID 39309429, 2024). "To further validate our in vitro findings, we investigated the role of DSCC1 in regulating tumor growth and metastasis in vivo." (PMID 39309429, 2024). "More studies are needed to determine its potential as a therapeutic target and investigate how DSCC1 regulates critical downstream biological processes and signaling to govern tumor initiation and development." (PMID 39768811, 2024). "Multivariate regression analysis confirmed these factors as independent risk factors for GC progression (P < 0.05): tumor size, lymph nodes metastasis, distant metastases, TNM stage, E2F4 expression, and DSCC1 expression." (PMID 39309429, 2024). "DSCC1 has been investigated as a potential tumor biomarker for early diagnosis and prognosis in a few studies." (PMID 39768811, 2024). "This comprehensive set of experiments with mouse and human models convincingly demonstrates that DSCC1 is critical for genome stability and a tumor suppressor." (PMID 38877011, 2024). "The results of DSCC1 evaluation in this study revealed that DSCC1 is highly expressed in invasive BC and correlated with aggressive features of the tumor at the mRNA and protein levels." (PMID 39768811, 2024). "There were 11 DEGs associated with tumor cell differentiation and dedifferentiation between EGFP- CD44-/CD24- cells and EGFP+ CSCs and they included RHBDL2, HIST1H4H, DSCC1, ZNF710, ATP8B3, and others." (PMID 34318746, 2021). "The immunohistochemical analysis demonstrated that DSCC1 was strongly expressed in the cytosol of tumor regions, whereas normal tissue displayed the majority of DSCC1 localized to the nucleus, with weak signals observed in the cytosol." (PMID 31762824, 2019). "Quantitative comparison of the mRNA expression of DSCC1 by qPCR (n=50) revealed that the expression of DSCC1 at the tumor site was increased by ~2.9 times." (PMID 31762824, 2019). "As anticipated, DSCC1 knockdown significantly slowed tumor growth in the nude mice." (PMID 39309429, 2024). "High DSCC1 protein expression was significantly associated with high tumor grade (p < 0.001), negative hormone receptor (ER−: p = 0.007, PR−: p = 0.005), and high Ki67 (p = 0.036)." (PMID 39768811, 2024). "Additionally, Western blot analysis showed that DSCC1 knockdown reduced its expression in the tumor tissues." (PMID 39309429, 2024). "In both cohorts, a significant correlation was observed between high DSCC1 mRNA expression and large tumor size, high tumor grade, LVI positivity, hormone receptor negativity (ER−/PR−; all p < 0.001), and HER2 positivity (p < 0.001 in METABRIC and p = 0.027 in TCGA)." (PMID 39768811, 2024). "To date, no studies have addressed the prognostic significance of DSCC1 in invasive BC and its association with aggressive tumor behavior." (PMID 39768811, 2024). "Furthermore, DSCC1 suppresses ER stress and promotes LUAD progress via interacting with HSP90AB1 and activating STAT3, and DSCC1 inhibits tumor immune infiltration via regulating HSP90AB1/STAT3/PD-L1 axis." (PMID 37742009, 2023). "In this study, we found that DSCC1 was negatively correlated with tumor-infiltrating immune cells." (PMID 37742009, 2023). "In contrast, DSCC1 overexpression could upregulate biomarkers of stem-like tumor cells in LUAD cells." (PMID 37742009, 2023). "DSCC1 expression levels were higher in tumor tissues compared with normal tissues." (PMID 31762824, 2019).
tumor (continued). "By disrupting DSCC1’s functions, tumor cells’ proliferation and survival may be influenced." (PMID 39768811, 2024). "In addition, DSCC1 promotes tumor growth in the onset and progression of BC and may also be a potential biomarker for therapeutic intervention in BC." (PMID 39768811, 2024). "Furthermore, DSCC1 silence could downregulate the expression of multiple biomarkers of stem-like tumor cells, including SOX2, NANOG, and Oct-4." (PMID 37742009, 2023). "Furthermore, DSCC1 expression may be elevated in specific tumor types." (PMID 39768811, 2024). "Univariate regression analysis identified several factors affecting OS (P < 0.05): tumor size, lymph nodes metastasis, distant metastases, TNM stage (stages I and II vs. stages III and IV), E2F4 expression (low vs. high), and DSCC1 expression (low vs. high)." (PMID 39309429, 2024). "To date, no studies have addressed the prognostic significance of DSCC1 in invasive BC and its correlation with aggressive tumor behavior." (PMID 39768811, 2024). "High DSCC1 expression may promote the activity of the HER2 signaling pathway, which can trigger the tumor microenvironment to promote tumor cell proliferation, invasion, and metastasis." (PMID 39768811, 2024). "Notably, when DSCC1- or CTF18-knockdown cells were xenografted into athymic nude mice, shDSCC1 cells significantly inhibited tumor formation, whereas shCTF18 cells formed a mass of granules." (PMID 31762824, 2019). "However other clinicopathological features, such as sex, age, location, tumor grade and TNM stage, were not significant in patients exhibiting elevated cytosolic or nuclear DSCC1 levels." (PMID 31762824, 2019).
DSCC1 also shares sentences with these, for which no sentence is quoted: chordoma (1 paper); gastritis (1); gastrointestinal disease (1); rectum adenocarcinoma (1).